TMEM64 (transmembrane protein 64)
Description:
Positively regulates TNFSF11-induced osteoclast differentiation. Acts as a regulator of TNFSF11-mediated Ca(2+) signaling pathways via its interaction with SERCA2 which is critical for the TNFSF11-induced CREB1 activation and mitochondrial ROS generation necessary for proper osteoclast generation. Association between TMEM64 and SERCA2 in the ER leads to cytosolic Ca (2+) spiking for activation of NFATC1 and production of mitochondrial ROS, thereby triggering Ca (2+) signaling cascades that promote osteoclast differentiation and activation. Negatively regulates osteoblast differentiation and positively regulates adipocyte differentiation via modulation of the canonical Wnt signaling pathway. Mediates the switch in lineage commitment to osteogenesis rather than to adipogenesis in mesenchymal stem cells by negatively regulating the expression, activity and nuclear localization of CTNNB1.
Synonyms: DKFZp762C1112
Tractability: Antibody: UniProt predicts a signal peptide or a membrane-spanning region. PROTAC: ubiquitination databases record sites on it.
Gene: Protein-coding gene on chromosome 8 (90,621,995 to 90,791,632, reverse strand). Ensembl gene ENSG00000180694.
Subcellular location: Membrane; Endoplasmic reticulum
Gene Ontology:
Biological process: negative regulation of canonical Wnt signaling pathway; negative regulation of osteoblast differentiation; positive regulation of bone resorption; positive regulation of fat cell differentiation; positive regulation of osteoclast differentiation; regulation of cytosolic calcium ion concentration
Cellular component: endoplasmic reticulum; membrane
Genetic constraint (gnomAD): Loss-of-function variants: 19 observed, 20.6 expected, observed/expected ratio (o/e) 0.92, 90% interval 0.64 to 1.35. The synonymous counts are far from expectation, so gnomAD's model fits this gene poorly and the ratio says little. Missense variants: 479 observed, 462.11 expected, observed/expected ratio (o/e) 1.04, 90% interval 0.96 to 1.12. Synonymous variants: 254 observed, 205.54 expected, observed/expected ratio (o/e) 1.24, 90% interval 1.12 to 1.37.
Homologues: Orthologues: chimpanzee TMEM64 (99% identical), macaque TMEM64 (97% identical), pig TMEM64 (92% identical), rat Tmem64 (91% identical), mouse Tmem64 (89% identical), guinea pig TMEM64 (86% identical), dog TMEM64 (84% identical), zebrafish tmem64 (60% identical), tropical clawed frog tmem64 (57% identical), rat AABR07002627.1 (47% identical), Drosophila melanogaster CG11367 (25% identical). Paralogues in human: TMEM41A (15% identical), TMEM41B (11% identical).
Diseases named in the same sentence as TMEM64 in open-access papers:
TMEM64 is named in the same sentence as 17 diseases in open-access papers, as found by Europe PMC text mining. Sharing a sentence is not in itself a finding about the gene and the disease. The quoted sentences say what the papers report.
breast carcinoma (1 paper, 2022). "We constructed a novel 6-gene signature (SQSTM1, GDF9, LINC01125, PTGS2, GVINP1, and TMEM64) and used an XGBoost model to predict the metastatic status in breast cancer (AUC = 0.82)." (PMID 35436939, 2022). "We speculated whether these 5 genes, LINC01125, GDF9, PTGS2, GVINP1, and TMEM64, contributed to breast cancer metastasis because of immune dysfunction and conducted an exploration from the immune cell perspective." (PMID 35436939, 2022). "In conclusion, our present research constructed a novel 6-gene signature (SQSTM1, GDF9, LINC01125, PTGS2, GVINP1, and TMEM64) by feature importance score and used an XGBoost model to predict the metastatic status in breast cancer (AUC = 0.82, higher than the previous studies to our knowledge)." (PMID 35436939, 2022). "Researches on gene LINC01125, gene GDF9 and gene GVINP1 is very limited, no studies have shown that there is a link between gene TMEM64 and breast cancer." (PMID 35436939, 2022).
breast tumor (1 paper, 2022). "To elucidate the biological functions of SQSTM1, GDF9, LINC01125, PTGS2, GVINP1, and TMEM64 in breast tumor cells, we knocked down the expression of the 6-gene signature using shRNA or the negative control in MCF-7 cell lines to assess cell proliferation, migration and invasion in vitro." (PMID 35436939, 2022).
chronic kidney disease (1 paper, 2023). Impairment of the renal function secondary to chronic kidney damage persisting for three or more months. "Diseases and phenotypes associated with TMEM64 include cholesterol, creatinine, chronotype, and serum metabolite concentrations in chronic kidney disease." (PMID 37669986, 2023).
glioma (1 paper, 2025). A benign or malignant brain and spinal cord tumor that arises from glial cells (astrocytes, oligodendrocytes, ependymal cells). "Previous studies have shown that various oncogenes, such as SRPK1 and TMEM64, promote glioma proliferation, migration, and invasion by activating Wnt/β‐catenin signaling." (PMID 40589077, 2025).
hepatocellular carcinoma (1 paper, 2025). A malignant tumor that arises from hepatocytes. "Gene perturbation analysis revealed that TMEM64 expression is increased upon hepatocyte nuclear factor 4 alpha (HNF4α) depletion in HepG2 hepatocellular carcinoma cells." (PMID 41472678, 2025).
Hyperglycemia (1 paper, 2025). An increased concentration of glucose in the blood. "Additional associations with metabolic disorders such as hyperglycemia (SV = 1.32), insulin resistance (SV = 1.20), and hypertriglyceridemia (SV = 1.13) further implicate TMEM64 in glucose and lipid metabolism." (PMID 41472678, 2025).
Osteopenia (1 paper, 2019). Osteopenia is a term to define bone density that is not normal but also not as low as osteoporosis. "The levels of mRNAs of annexin A1, S100A4, and TMEM64 in human peripheral blood mononuclear cells were evaluated among 48 osteopenia and 23 osteoporosis patients compared to 17 nonosteoporotic controls." (PMID 31814858, 2019). "The reduction of neither TMEM64 nor S100A4 discriminated well nonosteoporotic controls from osteopenia (area under the ROC curves, 0.6 and 0.55, respectively, not shown) or osteopenia and osteoporosis combined (area under the ROC curves, 0.646 and 0.627, respectively, not shown)." (PMID 31814858, 2019). "Thus, the aim of this study was to find out whether the levels of mRNAs for annexin A1, S100A4, and TMEM64 were significantly changed in the PBMCs of participants with osteopenia or with osteoporosis compared to nonosteoporotic controls." (PMID 31814858, 2019). "Neither TMEM64 nor S100A4 mRNAs discriminated well nonosteoporotic controls from osteopenia (area under the ROC curves, 0.614 and 0.543, respectively, not shown) or osteopenia and osteoporosis combined (area under the ROC curves, 0.667 and 0.618, respectively, not shown)." (PMID 31814858, 2019).
osteoporosis (1 paper, 2019). A condition of reduced bone mass, with decreased cortical thickness and a decrease in the number and size of the trabeculae of cancellous bone (but normal chemical composition), resulting in increased fracture incidence. "This study is aimed at investigating the level of calcium-binding/associated proteins, annexin A1, S100A4, and TMEM64, in peripheral blood mononuclear cells associated with osteoporosis and its clinical significance." (PMID 31814858, 2019). "ROC analysis showed that the reduction in the level of mRNA for annexin A1, S100A4, or TMEM64 in the patients' peripheral blood mononuclear cells has a good diagnostic value for osteoporosis." (PMID 31814858, 2019). "The results show for the first time that calcium-binding/associated proteins, annexin A1 and TMEM64, could be future diagnostic biomarkers for osteoporosis." (PMID 31814858, 2019). "For TMEM64 mRNA in PBMCs, the observed reduction in the level with osteoporosis in the present experiments seems unexpected in view of previous results with TMEM64 knockout mice, in which reduced levels of TMEM64 mRNA resulted in a phenotype of increased bone mass." (PMID 31814858, 2019). "The levels of mRNAs for annexin A1, S100A4, and TMEM64 were reduced in PBMCs from osteoporosis patients compared to nonosteoporotic controls; thus, the presence of these mRNAs marked the nonosteoporotic condition." (PMID 31814858, 2019). "Three mRNAs, encoding calcium-binding/associated proteins, ANXA1, S100A4, and TMEM64, were found to be at a lower level in the PBMC preparations from osteoporosis patients than nonosteoporotic controls." (PMID 31814858, 2019). "Annexin A1 and TMEM64 mRNAs were also significantly reduced in female osteoporosis patients over the age of 50 years compared to nonosteoporotic controls (one-way ANOVA, P = 0.004 and P = 0.0037, respectively)." (PMID 31814858, 2019).
tumor (1 paper, 2022). "In summary, we assigned the effects of SQSTM in tumor cells as a risk factor and the effects of other 5 genes (GDF9, LINC01125, PTGS2, GVINP1, and TMEM64) in immune cells as protective factors." (PMID 35436939, 2022). "In general, the effects of SQSTM in tumor cells are assigned as a risk factor, while the effects of the other 5 genes (GDF9, LINC01125, PTGS2, GVINP1, and TMEM64) in immune cells are assigned as protective factors." (PMID 35436939, 2022).
TMEM64 also shares sentences with these, for which no sentence is quoted: acute liver failure (1 paper); colon cancers (1); hypertriglyceridemia (1); immune dysfunction (1); Insulin resistance (1); liver diseases (1); liver neoplasm (1); metabolic disorders (1).